TRIM64 (tripartite motif containing 64)
Synonyms: C11orf28; TRIM64A
Tractability: No criterion of Open Targets' tractability assessment is met for any kind of drug.
Gene: Protein-coding gene on chromosome 11 (89,966,037 to 89,974,072, forward strand). Ensembl gene ENSG00000204450.
Gene Ontology:
Molecular function: ubiquitin protein ligase activity; metal ion binding; zinc ion binding
Biological process: innate immune response; regulation of gene expression
Cellular component: cytoplasm
Homologues: Paralogues in human: TRIM64B (98% identical), TRIM64C (91% identical), TRIM43 (48% identical), TRIM43B (48% identical), TRIM51 (47% identical), TRIM49 (46% identical), TRIM49C (46% identical), TRIM49B (46% identical), TRIM49D1 (44% identical), TRIM49D2 (44% identical), TRIM51G (44% identical), TRIM77 (41% identical), and 68 more.
Diseases named in the same sentence as TRIM64 in open-access papers:
TRIM64 is named in the same sentence as 3 diseases in open-access papers, as found by Europe PMC text mining. Sharing a sentence is not in itself a finding about the gene and the disease. The quoted sentences say what the papers report.
atherosclerosis (3 papers, 2023 to 2025). A disease characterized by the build-up of fatty material and calcium deposition in the arterial wall resulting in partial or complete occlusion of the arterial lumen. "Therefore, the TRIM64 localization during development of atherosclerosis and the association between NF-κB and TRIM64 in clinical samples would be further supplemented." (PMID 36229750, 2023). "In THP-1 derived FMs, ox-LDL promoted TRIM64 expression, subsequently enhanced pyroptosis, and inflammation in the development of atherosclerosis." (PMID 40264781, 2025). "We established TRIM64’s function and our results shed light on future therapeutic approaches towards atherosclerosis." (PMID 36229750, 2023). "To examine the role of TRIM64 in atherosclerosis in THP-1 macrophages treated with ox-LDL, we first designed 3 small interference RNAs (shRNAs) targeting TRIM64." (PMID 36229750, 2023). "In summary, our study has illuminated the relationship between TRIM64 and the NF-κB regulatory axis in atherosclerosis, suggesting that TRIM64 may serve as a potential target for future atherosclerosis therapy." (PMID 36229750, 2023). "Our study revealed an interaction between TRIM64 and NF-κB in the development of atherosclerosis." (PMID 36229750, 2023). "ox-LDL promotes TRIM64 expression, suggesting a potential role of TRIM64 in atherosclerosis." (PMID 36229750, 2023). "Therefore, we hypothesized that TRIM64 contributes to atherosclerosis through the NF-κB/IκBα pathway." (PMID 36229750, 2023). "Hence, oxLDL induces the activation of TRIM64/NF-κB/NLRP3 signaling in macrophages, thereby releasing proinflammatory cytokines, which promote plaque inflammation and atherosclerosis." (PMID 39528464, 2024). "A recent study on Apoe−/− mice revealed that oxLDL triggered the upregulation of TRIM64 expression, the activation of NF-κB signaling and NLRP3 inflammasome in macrophages, ultimately resulting in plaque inflammation and the development of atherosclerosis." (PMID 39528464, 2024). "Future investigations are required to study whether TRIM64 and TRIM7 work together in atherosclerosis development." (PMID 36229750, 2023).
cancer (1 paper, 2023). A tumor composed of atypical neoplastic, often pleomorphic cells that invade other tissues. "While the biological functions of TRIM64 have been partially explored regarding cancers, these genes in livestock remain unknown." (PMID 37959106, 2023).
TRIM64 also shares sentences with these, for which no sentence is quoted: tumor (1 paper).